OGT (O-linked N-acetylglucosamine (GlcNAc) transferase)
Diseases named in the same sentence as OGT in open-access papers (continued):
Sharing a sentence is not in itself a finding about the gene and the disease.
infection (11 papers, 2014 to 2025). The state of being infected such as from the introduction of a foreign agent such as serum, vaccine, antigenic substance or organism. "Using Sendai virus (SeV) as a model, they showed that O-GlcNAcylation declines during infection, partly due to host-mediated downregulation of OGT transcription." (PMID 41227388, 2025). "Increased OGT expression induced by infection of adenovirus prolonged calcium transient decays and significantly decreased cardiac type sarco/endoplasmic reticulum Ca2+-ATPase (SERCA2a) protein levels." (PMID 37033243, 2023). "The results showed that the apoptosis of T24 and UMUC-3 cells were enhanced after the downregulation of OGT following infection with LV-sh-OGT compared with LV-sh-NC." (PMID 30453909, 2018). "Chlamydia trachomatis requires OGT activity and vimentin glycosylation sites to maintain inclusion integrity during infection." (PMID 29513221, 2018). "Therefore, we examined the expression of immunoreactive OGT protein at various times after infection as indicated." (PMID 33603735, 2020). "Moreover, the colony formation assay indicated the proliferation of T24 and UMUC-3 cells was suppressed dramatically following infection with LV-sh-OGT." (PMID 30453909, 2018). "Additionally, in SY5Y cells, we used adenoviral-mediated OGT or OGA infection to alter O-GlcNAc levels." (PMID 25520704, 2014). "However, it has been observed that OGT is important for protecting the mycobacterial DNA at different stages of the infection and that OGT expression undergoes a fine-tuning regulation during the infection in response to alkylating agents." (PMID 29389854, 2018). "The effects of OGT and OGA inhibitors on A4 O-GlcNAcylation were determined by adding the drugs to cells prior to infection with vA4-YFP and purifying the A4-YFP fusion protein." (PMID 40407344, 2025). "As no other candidate viral OGT existed, we considered it likely that the cellular enzyme catalyzed O-GlcNAcylation of A4 during infection." (PMID 40407344, 2025). "Surprisingly, we found that transcription of OGT decreased dramatically at all time points examined, most notably at the earliest time point after infection (i.e., 4 h)." (PMID 33603735, 2020). "Here, we report that transcription of OGT is dramatically decreased at early time points after infection with an RNA virus; this contributes to the depletion of the O-GlcNAcylation of MAVS at later time points after infection, which serves to promote an innate immune response." (PMID 33603735, 2020).
metabolic disease (11 papers, 2019 to 2025). A congenital disorder (due to inherited enzyme abnormality) or acquired (due to failure of a metabolically important organ) disorder resulting from an abnormal metabolic process. "Establishing a mechanism for OGT-driven tumorigenesis would provide therapeutic insight into metabolic disease and TNBC risk." (PMID 37231419, 2023). "The enzymatic activity of OGT is highly affected by glucose metabolism in a given cell, and changes to OGT function have been associated with metabolic disorders, including diabetes." (PMID 36941297, 2023). "Our initial data in mice suggested that OGT was upregulated in DIO animals compared to lean littermates, addressing one of the many missing mechanistic links connecting this metabolic disease with TNBC risk and progression." (PMID 37231419, 2023). "However, more recent work using adipocyte-specific OGT KO mice has confirmed a crucial role of adipose tissue O-GlcNAcylation in the regulation of adiposity and its involvement in metabolic diseases." (PMID 36058931, 2022). "A constitutive OGA knockout mouse exhibits metabolic disorders, perinatal lethality, organ defects, and tissue-specific dysregulation of O-GlcNAc homeostasis, whereas OGT depletion decreases the proliferation of embryonic neural stem cells and inhibits the migration of newborn neurons." (PMID 35887161, 2022). "However, recent data, obtained with OGT- and OGA-KO mice models, showed that a simplistic scheme in which increased O-GlcNAcylation is considered as deleterious with regard to metabolic diseases does not stand anymore." (PMID 36058931, 2022).
neurodevelopmental disorder (6 papers, 2018 to 2025). A behavioral and cognitive disorder with onset during the developmental period that involves impaired or aberrant development of intellectual, motor, or social functions. "Mutations in either OGT or OGA segregate with neurodevelopmental disorders, and knock-out of the Ogt gene is embryonic lethal in mice, underscoring the essentiality of O-GlcNAcylation in eukaryotic biology." (PMID 40592469, 2025). "The involvement of OGT in numerous epigenetic pathways, with the propensity of epigenetic disorders to manifest in neurodevelopmental disorders suggests possible mechanisms causing this form of XLID." (PMID 33329753, 2020). "Recently, OGT has been linked to a rare neurodevelopmental disorder known as OGT-XLID, which we hypothesize could be caused by dysfunction of the essential role of O-GlcNAc as an epigenetic regulator, the focus of this review." (PMID 33329753, 2020). "We discuss how placental OGT could be a marker for placental stress contributing toward neurodevelopmental disorders." (PMID 33329753, 2020). "Taken together these results suggest that normal function of placental OGT and the subsequent trans-placental signals are critical for the developing brain, and that sex differences in placental OGT may mediate the increased male vulnerability to neurodevelopmental disorders." (PMID 29967448, 2018).
immune dysfunction (3 papers, 2014 to 2021). "An improved understanding of O-GlcNAcylation and its role in RLR-mediated signaling in RNA virus-infected cells may present OGT as a potential therapeutic target for the treatment of patients with immune dysfunction." (PMID 33603735, 2020).
adenocarcinoma (2 papers, 2016 to 2024). A common cancer characterized by the presence of malignant glandular cells. "However, immunohistochemistry of pre- and post-treatment specimens from two NEPC patients showed that both O-GlcNAcylation levels and OGT expression were elevated in post-treatment NEPC tissue compared to pre-treatment adenocarcinoma tissue." (PMID 39505875, 2024).
hematologic malignancies (2 papers, 2021 to 2024). "This review summarizes the complexes involved in the assembly of OGT in cells and the role of related OGT complexes in hematological malignancies." (PMID 38931332, 2024). "The apparent importance of O-GlcNAcylation in hematologic malignancies suggests they may be useful models for evaluating OGT modulators in clinical trials." (PMID 34868034, 2021).
neurological disease (2 papers, 2021 to 2022). "Functional analysis of these genes showed that UQCRH participates in cardiac muscle contraction, PPA2 is closely related to sudden cardiac failure (SCD), and OGT, as the interacting gene partner of PANO1, is associated with neurological disease." (PMID 34290742, 2021).
genetic disorder (1 paper, 2020). "We focus on a rare human genetic disorder where mutant forms of OGT are inherited or acquired de novo." (PMID 33329753, 2020).
heart disease (1 paper, 2021). "Another factor that influences heart disease is inflammation, OGT mediates LPS-induced nuclear transcription factor kappa-beta-p65 (NF-κβ/p685) entry and activation of endothelial cells; this was proven using ST045849 (10 μM), a potent OGT inhibitor." (PMID 34869586, 2021).
OGT also shares sentences with these, for which no sentence is quoted: esophageal cancer (4 papers); cardiovascular disease (3); Glucose intolerance (3); intellectual disability syndrome (3); chronic lymphocytic leukemia (2); colon adenocarcinoma (2); diabetic retinopathy (2); melanoma (2); ovarian tumor (2); pancreatic ductal adenocarcinoma (2); Parkinson's (2); rectal cancer (2); stomach adenocarcinoma (2); X-linked intellectual disability syndrome (2); acute coronary syndrome (1); aneurysm (1); Arts syndrome (1); autism (1); bile duct carcinoma (1); breast (1); breast adenocarcinoma (1); cerebral malaria (1); cervical squamous cell carcinoma (1); ciliopathy (1); cognitive disorder (1); cryptorchidism (1); developmental disability (1); diabetic cardiomyopathy (1); diabetic nephropathy (1); dyslipidemia (1).
A further 28 diseases each share a sentence with OGT in 1 paper.